SNORD116-1 (small nucleolar RNA, C/D box 116-1)
Synonyms: HBII-85-1; PWCR1
Gene: Small nucleolar RNA gene on chromosome 15 (25,051,477 to 25,051,571, forward strand). Ensembl gene ENSG00000207063.
Gene Ontology:
Biological process: RNA processing
Cellular component: nucleolus
Homologues: Orthologues: chimpanzee SNORD116 (99% identical), macaque SNORD116 (97% identical), rabbit SNORD116 (88% identical), rabbit SNORD116 (87% identical), rabbit SNORD116 (86% identical), rabbit SNORD116 (85% identical), rabbit SNORD116 (84% identical), rabbit SNORD116 (83% identical), rabbit SNORD116 (80% identical), rabbit SNORD116 (78% identical), rabbit SNORD116 (76% identical). Paralogues in human: SNORD116-3 (97% identical), SNORD116-9 (97% identical), SNORD116-2 (96% identical), SNORD116-5 (96% identical), SNORD116-7 (96% identical), SNORD116-6 (95% identical), SNORD116-8 (95% identical), SNORD116-4 (94% identical), SNORD116-14 (86% identical), SNORD116-17 (85% identical), SNORD116-19 (85% identical), SNORD116-15 (84% identical), and 20 more.
Diseases named in the same sentence as SNORD116-1 in open-access papers:
SNORD116-1 is named in the same sentence as 3 diseases in open-access papers, as found by Europe PMC text mining. Sharing a sentence is not in itself a finding about the gene and the disease.
SNORD116-1 shares sentences with these, for which no sentence is quoted: Prader-Willi syndrome (3 papers); Growth Deficiency (1); Hyperphagia (1).